BRCA1 (BRCA1 DNA repair associated)
Diseases named in the same sentence as BRCA1 in open-access papers (continued):
Sharing a sentence is not in itself a finding about the gene and the disease.
ovarian carcinoma (continued). "Recent randomized clinical trial data in ovarian cancer has showed that HRD-positive tumors without BRCA1/2 alterations respond favorably to PARP-inhibitors as first-line maintenance therapy." (PMID 32719340, 2020). "We found that three women with ovarian cancer (II1, II3, and II5) in the family carried BRCA1 (3326A>T) and BRCA2 (1342A>C) mutations, and no BRCA1 and BRCA2 mutations were detected in healthy individuals." (PMID 32356124, 2020). "Several studies have shown that among ovarian cancer patients, BRCA1 and especially BRCA2 carriers respond better than non-carriers to platinum-based chemotherapy and have prolonged survival." (PMID 32341426, 2020). "BRCA1 and BRCA2 are the most incriminated genes in inherited breast/ovarian cancers." (PMID 32025337, 2020). "Similarly, other groups have reported reduced time to results with oncology clinic-based BRCA1 and BRCA2 testing for ovarian cancer patients." (PMID 32028617, 2020). "In addition to our BRCA1/2-like tests, other (commercially) available HRD tests are on the market for breast and ovarian cancer." (PMID 32711554, 2020). "In contradiction to these findings, a study of 108 patients with breast and/or ovarian cancer and 60 controls found no subjects with promoter hypermethylation in BRCA1." (PMID 33396385, 2020). "The prospective cohort study of the German Consortium Hereditary Breast and Ovarian Cancer (GC-HBOC) is conducting the HerediCaRe registry, which is part of the International BRCA1 and BRCA2 Carrier Cohort Study (IBCCS), one of the largest registries for hereditary breast and ovarian cancer." (PMID 32140806, 2020). "One such initiative, Traceback Testing, which is funded by the National Cancer Institute, recommends offering at least BRCA1 and BRCA2 testing to all women diagnosed with ovarian cancer identified through pathology or tumor registries, along with follow-up testing and counseling of family members." (PMID 30832243, 2019). "The PARP inhibitor niraparib was also tested for use as maintenance therapy in platinum-sensitive ovarian cancer, regardless of its BRCA1 status." (PMID 31640753, 2019). "Our findings demonstrated that circPLEKHM3 functions as a tumor suppressor in ovarian cancer cells by targeting the miR-9/BRCA1/DNAJB6/KLF4/AKT1 axis and may be used as a prognostic indicator and therapeutic target in ovarian cancer patients." (PMID 31623606, 2019). "The recognition of strong familial clustering of breast and ovarian cancer, followed by the discovery of the BRCA1 and BRCA2 (BRCA1/2) genes in 1994 and 1995, respectively, has led to the study and characterization of BRCA1/2-related hereditary breast and ovarian cancer syndrome (HBOC)." (PMID 31892343, 2019). "Women with triple negative breast cancer (TNBC) who are diagnosed at an early age are candidates for BRCA1 genetic testing, even if they do not have a family history of breast or ovarian cancer." (PMID 31244284, 2019). "In 39% of the 77 centers, ovarian cancer patients undergo germline BRCA1/2 testing without previous genetic counselling and the test is prescribed directly by the oncologist." (PMID 31600986, 2019). "A significant correlation was revealed between single nucleotide polymorphisms of DNA double-strand break repair genes via homologous recombination (HR) XRCC3-Thr241Met (rs861539), XRCC2--41657C/T (rs718282), BRCA1-Q356R (rs1799950) and RAD51–135 G/C (rs1801320) and ovarian cancer development." (PMID 30712190, 2019). "Among women who tested positive for either a BRCA1 or BRCA2 gene mutation, 56% had no previous family history of breast or ovarian cancer." (PMID 31061661, 2019). "Isolated lymph node relapse cases demonstrated greater tumor-infiltrating lymphocyte burden at diagnosis, but did not demonstrate significant enrichment or depletion of BRCA1/2 mutation or gain of CCNE1, both known to be prognostic in ovarian carcinoma." (PMID 31055034, 2019).
ovarian carcinoma (continued). "There will be a subgroup of BRCA1 or 2‐positive patients with ovarian cancer without a family history of cancer, and these patients would have been missed if using family history of cancer and/or age at onset as selection criteria for testing." (PMID 30821131, 2019). "In this study, we determined if BRCA1 partners involved in DNA double-strand break (DSB) and mismatch repair (MMR) may contribute to breast and ovarian cancer development." (PMID 30283497, 2018). "We were not able to analyze the expression level of BRCA1 in ovarian cancer patients due to lack of RNA samples." (PMID 30049288, 2018). "Although one of our studies recruited individuals with a history of familial breast and ovarian cancer, eligibility required documentation of negative germline BRCA1/2 genetic testing." (PMID 30583724, 2018). "A new diagnosis of male breast cancer prompted BRCA1/2 testing in the 4 individuals without a family history of breast and ovarian cancer." (PMID 29433453, 2018). "BRCA1 expression predicts the outcome of breast, lung, and ovarian cancer treatment with DNA-damage-based therapy and depending on the type of chemotherapeutics, BRCA1 can have either a positive or negative role in mediating chemo-sensitivity." (PMID 29932172, 2018). "Indeed, in the TCGA data we observe that increased deletions in BRCA1 are correlated with CNV standard deviation, suggesting that the ovarian cancer effect is mediated by the tandem duplicator phenotype." (PMID 30061557, 2018). "The increase in local IFNγ in response to the combination of anti-CTLA-4 and PARPis was sufficient to inhibit tumor growth, but this combination had no such effect on BRCA1-sufficient ovarian cancer cells that were inoculated into the mice." (PMID 30487462, 2018). "The contribution of BRCA1 and BRCA2 mutations to breast and ovarian cancer incidence has not been well explored in Asian population, where both cancer incidence and mutation prevalence are lower compared to western countries." (PMID 29861850, 2018). "FMR1 may be involved in the regulation of ATR-dependent signaling pathways such as BRCA1 phosphorylations and interact with BRCA in human Ovarian Cancers." (PMID 30286182, 2018). "In this study, we aimed to determine if BRCA1 partners involved in HR, NHEJ, and MMR may contribute to breast and ovarian cancer development." (PMID 30283497, 2018). "During evaluation of an amplicon-based breast and ovarian cancer gene panel with positive controls, we encountered a false-negative result for a BRCA1 17 nt deletion (c.1620_1636del)." (PMID 28484262, 2017). "We previously reported that BRCA1 expression paralleled cell proliferation in benign and borderline ovarian epithelial tumors, but not in ovarian epithelial cancers." (PMID 28270171, 2017). "In this paper, we describe our findings on the occurrence of OEIs, and on cell proliferation, cell apoptosis, and BRCA1 expression of OEI epithelial cells in ‘normal’ ovaries from women with no known history of familial ovarian cancer." (PMID 28270171, 2017). "Neighbor of Brca1 gene (NBR1) has been of interest due to its position close to BRCA1, but has no involvement in breast or ovarian cancer." (PMID 29212269, 2017). "Results of a large clinical trial using single agent Niraparib in relapsed ovarian cancer demonstrated that it was a safe and highly effective agent in ovarian cancer, regardless of HR or BRCA1/2 status." (PMID 28756516, 2017). "The accelerated approval of olaparib by the FDA and EMA in patients with advanced BRCA1/2 mutation ovarian cancer (without specific platinum sensitivity status, FDA) heralded a new era in precision medicine in patients with advanced ovarian cancer." (PMID 28454085, 2017).
ovarian carcinoma (continued). "Genetic testing should therefore be offered to every patient with invasive epithelial ovarian cancer and limiting testing to BRCA1/2 seems to be not sufficient." (PMID 29053726, 2017). "In summary, this is the first study on BRCA1 expression, cellular proliferation and apoptosis in OEIs of patients without known history of ovarian cancer." (PMID 28270171, 2017). "The purpose of our study was to address the issue of missing heritability in ovarian cancer by focusing on 48 women with a personal history of OVCA and who were at high risk of genetic inheritance but had no known pathogenic variant in BRCA1/BRCA2." (PMID 28591191, 2017). "Risk reduction strategies are most relevant to women identified as carrying a BRCA1 or BRCA2 mutation who have not yet developed cancer and the role of risk-reducing surgery in the management of hereditary breast and ovarian cancer is already well established." (PMID 28780755, 2017). "Similar to BRCA1, BRCA2 dysfunction is commonly found in breast and ovarian cancer." (PMID 28471392, 2017). "In the current study, BRCA1 mutations were identified in 14.4 % of early-onset patients with TNBC, who had no family history of breast/ovarian cancer." (PMID 27553291, 2016). "A plethora of clinical studies have extensively documented occurrence of hypermethylation at the BRCA1 promoter leading to gene silencing in nonfamilial breast and ovarian cancers." (PMID 27356740, 2016). "Of women with ovarian cancer without reported previous BRCA1/2 testing, 13.4% (89/663) were positive." (PMID 26681312, 2016). "In clear contrast, dual ATM/ATR inhibition strongly potentiates the activity of both ETs against human cervical and ovarian carcinoma cells by efficiently blocking the formation of γ-H2AX, MDC1, BRCA1 and Rad51 foci following ET-exposure thereby resulting in extensive chromosome damage." (PMID 27029031, 2016). "The advantages of this approach were presented in our previous study, where more than one‐third of BRCA1/2‐positive patients had no family history of breast or ovarian cancer." (PMID 27167707, 2016). "Strikingly, this has not been observed in ovarian cancer hypermethylation groups when compared to unmethylated BRCA1 ovarian cancer patients." (PMID 27027444, 2016). "Among patients with specific cancers, yields were 9.7, 13.4, and 14.8% in patients with breast, ovarian, and colon/stomach cancer, respectively (the patients with breast or ovarian cancer did not report previous BRCA1/2 testing)." (PMID 26681312, 2016). "Earlier reports from our group have established the ability of PB, a naturally occurring naphthoquinone to induce cytotoxicity specifically and selectively in BRCA1 defective ovarian cancers." (PMID 27229859, 2016). "Another study examined the ovarian cancer cell line SNU251, and found that a truncated and dysfunctional BRCA1 protein impaired sub-nuclear protein assembly required for DNA damage repair, and subsequently led to increased sensitivity of the cells to taxol therapy." (PMID 27191893, 2016). "HBOC patients do not carry a BRCA1 or BRCA2 mutation but have an increased risk of developing breast and ovarian cancer." (PMID 26768420, 2016). "Hence, the purpose of our work was to screen the entire BRCA1 and BRCA2 genes in a series of patients with epithelial ovarian cancer unselected for age or family history for breast and/or ovarian cancer treated in Brazil." (PMID 27914478, 2016). "Twenty-four patients with ovarian cancer treated between 2000 and 2009 who tested positive for BRCA1/2 mutation (BRCA+) and a control group of 64 age-matched patients with no family history of breast/ovarian cancer (controls) were enrolled." (PMID 27350785, 2016).
ovarian carcinoma (continued). "It is also important to note that none of the studies summarized above reports any data on BRCA1 or BRCA2 mutation carriers and the results should only be generalized to women at population-level risk for ovarian cancer." (PMID 27231565, 2015). "Our results confirmed the findings that 30% of ovarian cancer patients carrying alterations in BRCA1/2 had a better prognosis than BRCA1/2 alteration non-carriers." (PMID 25537514, 2015). "Although BRCA1 and BRCA2 mutations account for only ∼27% of the familial aggregation of ovarian cancer (OvC), no OvC risk prediction model currently exists that considers the effects of BRCA1, BRCA2 and other familial factors." (PMID 26025000, 2015). "The rationale was based on the evidence that 50% of patients who carry BRCA1 and BRCA2 mutations have no close family history of breast or ovarian cancer." (PMID 25729421, 2015). "In addition, these findings suggest that DBC1 and BRCA1could be potential therapeutic targets for the treatment of ovarian carcinomas according to the expression status of DBC1 and BRCA1." (PMID 25823848, 2015). "Whereas homozygous inactivation of HR genes is usually embryonic lethal, heterozygous inactivation of for instance BRCA1 and BRCA2 does not interfere with cellular viability and rather predisposes to cancer, including breast and ovarian cancer." (PMID 25852742, 2015). "Analysis of the expanded 34 burden test genes revealed that patients with germline BRCA1 and BRCA2 truncations had significantly higher somatic mutation frequencies than cases without such changes in both breast and ovarian cancers." (PMID 26689913, 2015). "However, there has been no study to date on the role of DBC1 in ovarian tumorigenesis, its relation to BRCA1/2, and the prognostic significance of DBC1 in ovarian cancers." (PMID 25823848, 2015). "However, BRCA1 status and ALDH+ ovarian cancer stem-like cells maintenance and their resistance to chemotherapy has not been studied." (PMID 25216266, 2014). "Both analyses, thus, demonstrate that the combined presence of BRCA1/2 mutations and low FMR1 alleles actually appears to be less commonly associated with ovarian cancer than absence of both of these mutations in the same patient." (PMID 25036526, 2014). "Decrease or absence of the BRCA1 protein in sporadic breast and ovarian cancers suggests that BRCA1 functions as a tumor suppressor in nonhereditary tumors as well." (PMID 24704793, 2014). "A prevalence of 2.1% for BRCA1 large genomic rearrangements has been detected in Spanish hereditary breast/ovarian cancer families testing negative for point variations and small insertions/deletions in BRCA1 and BRCA2." (PMID 24906410, 2014). "When the same analysis was repeated for only 15 functionally oncogenic BRCA1/2 mutations, outcomes were very similar, 2/15 (13.3%) low FMR1 alleles in BRCA1/2 mutation carriers and 21/65 (32.3%) in ovarian cancer patients without BRCA1/2 mutations (P = 0.21)." (PMID 25036526, 2014). "Our group has previously reported that BRCA1/1a proteins, unlike K109R and C61G mutants, suppress growth of ovarian cancer cells by tethering Ubc9." (PMID 25594072, 2014). "ALDH1A1-knockdown induced DNA damage, evidenced by robust induction of γ-H2AX and BAX mediated apoptosis, with significant increases in BRCA1 expression, suggesting ALDH1A1-dependent regulation of cell cycle checkpoints and DNA repair networks in ovarian cancer stem-like cells." (PMID 25216266, 2014). "Of note, methylation of BRCA1, while frequent in sporadic ovarian cancer, it has not been reported in the hereditary type of the disease, nor in samples from women with a germ-line BRCA1 mutation." (PMID 24821107, 2014).
ovarian carcinoma (continued). "The knockdown and overexpression of BRCA1 were achieved using a lentiviral vector in 293 T cells, SKOV3 ovarian cancer cells, and primary non-mutated and BRCA1-mutated ovarian cancer cells." (PMID 24321281, 2013). "This study provides the results of our attempt to identify new BRCA1/2 mutations in HBOC patients and estimate their usefulness for molecular screening to spot hidden hereditary breast/ovarian cancer patients without a significant family history." (PMID 23767878, 2013). "It has also been noted that not all mutations in BRCA1 and BRCA2 are highly penetrant for breast or ovarian cancer." (PMID 24025454, 2013). "This early platinum failure is somewhat less common in BRCA1-related cancer than in non-hereditary ovarian cancer, and it seems unlikely that this failure is related to type of mutation (i.e. missense mutation) that was present in this patient." (PMID 23522120, 2013). "Given the fact that not the entire BRCA1 gene was screened, this percentage is probably an underestimate of the true frequency in ovarian cancer patients in our population." (PMID 23536787, 2013). "A 3020insCT/c.2901insCT frameshift mutation in exon 11 of the BRCA1, which has yet to be reported in the BIC database, was detected in a 55-year-old non-Ashkenazi Spanish female diagnosed with breast and ovarian cancer." (PMID 24137399, 2013). "Based on this figure, we support the recommendation of at least BRCA1 testing for all ovarian cancer patients, regardless of family history and age of diagnosis." (PMID 23536787, 2013). "However, to date, there have been few reports about the interactions between BRCA1 and EGFR in ovarian cancer." (PMID 24321281, 2013). "Knockdown or overexpression of BRCA1 was achieved by using a lentiviral vector in 293 T cells and SKOV3 ovarian carcinoma cells, and primary non-mutated and BRCA1-mutated ovarian cancer cells." (PMID 24321324, 2013). "Inherited BC risk is known to be associated with rare, highly penetrant variants, mainly single nucleotide polymorphisms (SNPs) and small insertions and deletions (indels) in BRCA1 and BRCA2, which account for nearly 20% of hereditary breast and/or ovarian cancer (HBOC) cases in Finland." (PMID 23967248, 2013). "Our analysis of rare CNVs in a small cohort of BRCA1/BRCA2 mutation-negative breast and/or ovarian cancer families suggests an intriguing excess in the proportion of rare CNVs compared to controls." (PMID 22314128, 2012). "In the NCIC study which correlated BRCA1 protein expression by ICH with corresponding clinical data, 251 ovarian cancer samples were analyzed using a mouse monoclonal BRCA1 antibody (MS110, Calbiochem, Germany) and 65% of the tumors showed no staining or very mild staining." (PMID 22253870, 2012). "In fact, when variants with particularly large effects do exist—such as APOE in Alzheimer’s disease, BRCA1 and BRCA2 in breast and ovarian cancer, and LRRK2 in Parkinson’s disease —previous authors have suggested simulations in lieu of their analytical approximation." (PMID 22827772, 2012). "The cell lines did not harbor the most commonly reported KRAS or BRAF mutations nor the most common BRCA1 and BRCA2 mutations identified in the French Canadian breast and ovarian cancer families." (PMID 22931248, 2012). "However, it is notable that although more than 10% women in whom an isolated TNBC develops at younger than 40 years old may have a mutation in BRCA1, insufficient evidence exists for those aged 41 to 50 years, with no family history of breast or ovarian cancer." (PMID 23116406, 2012).